KISS1 (KiSS-1 metastasis suppressor)
Diseases named in the same sentence as KISS1 in open-access papers (continued):
Sharing a sentence is not in itself a finding about the gene and the disease.
Obesity (continued). "Herein, we have shown a sexually dimorphic Kiss1/Kiss1r dysregulation in the rWAT of preeclamptic-like BPH/5 offspring and hypothesize that rWAT kisspeptin downregulation is linked to obesity in BPH/5 females." (PMID 37035685, 2023). "Moreover, SIRT1 SNPs have been linked with metabolic diseases such as obesity and type 2 diabetes, and animal studies have demonstrated that the SIRT1 protein advances puberty through the regulation of KISS1 expression, which stimulates GnRH secretion." (PMID 36046800, 2022). "Likewise, alterations in Kiss1 expression have also been reported in other situations of energy imbalance like diabetes and obesity." (PMID 29643834, 2018). "To investigate the mechanism by which maternal obesity disrupts reproductive function in offspring, we examined Kiss1 expression in the hypothalamic arcuate (ARC) and anteroventral periventricular (AVPV) nuclei, and posterodorsal medial amygdala (MePD) of pre-pubertal and young adult offspring." (PMID 28846730, 2017). "We hypothesized that in the presence of genetic or obesity-induced concurrent insulin and leptin resistance, Kiss1 neurons would be unable to maintain reproductive function." (PMID 25946091, 2015). "We used a diet-induced model of obesity to evaluate whether the ovarian Kiss1 system is affected by obesity, and, to investigate the association of the Kiss1 system with ovulatory disorders in female rats." (PMID 25542298, 2014). "Moreover, no obesity phenotype was reported in studies on human subjects with Gpr54 or Kiss1 mutations." (PMID 29593567, 2018). "Both observed that inhibition of GPR54/KiSS1 signaling could prevent obesity or diabetes." (PMID 29593567, 2018). "Our results confirmed that SCFAs can significantly decrease the gene expression of Kiss1, GPR54, GnRH and ERα in the hypothalamus of obesity-induced precocious puberty rats." (PMID 36568086, 2022). "Specifically, it has been identified that the ARC is the main integrator area of these effects, with epigenetic inhibition of Kiss1 by SIRT1 as a key mechanism by which nutritional signals and obesity influence puberty of children." (PMID 33572672, 2021). "Notably, our observations demonstrate that expression of ovarian Kiss1 and kisspeptin was suppressed during the ovulatory transition stage under conditions of obesity, indicating that the ovarian Kiss1 system is sensitive to obesity and may contribute to obesity-induced ovulatory dysfunction." (PMID 25542298, 2014). "In vivo, deletion of Mc4r from Kiss1 neurons in female mice replicates the reproductive impairments of Mc4r KO mice without inducing obesity." (PMID 40674128, 2025). "In rats fed a high-fat diet, there was a reduction in Kiss1 expression within WAT, suggesting that diet-induced obesity may disrupt Kiss1/Kiss1r signalling." (PMID 37732890, 2023). "In the present study, a high-fat diet model rather than an obesity model was established to investigate the effects of high-fat diet on Kiss-1-related indices and metabolism in the hypothalamus of male rats." (PMID 36001287, 2022). "Some studies found that obesity increased the production and expression of Kiss-1 genes, while other studies discovered no changes or even reduction in Kiss-1 gene expression among obese individuals." (PMID 31871451, 2019). "The aim of this study was to investigate the effects ofquercetin on obesity and ovarian tissue by analyzing the expression of genesinvolved in the hypothalamus-pituitary-gonadal axis, includingob-Rb, ob-Ra, and brain-derived neurotrophic factor(Bdnf), neuropeptide Y (NPY), andKisspeptin (Kiss-1)." (PMID 39983030, 2025). "In in vitro cell system, GPR54/KISS1 activation led to enhanced adipocyte differentiation and triglyceride accumulation, suggesting involvement of GPR54/KISS1 signaling in adipogenesis, lipid metabolism, and obesity development, through a mechanism independent of sex hormone signaling." (PMID 29593567, 2018).
Obesity (continued). "While we do not see a change in hypothalamic Kiss1 gene expression the changes in LH and FSH prior to obesity onset point towards impaired central leptin signaling." (PMID 28357399, 2017). "The removal of Nhlh2 from Kiss1 neurons did not induce any metabolic phenotype in Kiss1Cre:Nhlh2fl/fl mice under regular or HFD chow, which supports a role for Nhlh2 in POMC neurons in the obesity phenotype of whole-body KOs." (PMID 34494548, 2021).
hypogonadotropic hypogonadism (34 papers, 2011 to 2026). Abnormal ovarian or testicular function due to insufficient hormonal stimulation from the hypothalamic-pituitary axis. "We identified a novel heterozygous KISS1 variant c.-7C>T in two brothers diagnosed with hypogonadotropic hypogonadism." (PMID 41786302, 2026). "Mutations in the Kiss1 gene have been linked to hypogonadotropic hypogonadism and pubertal developmental disorders in humans." (PMID 40591449, 2025). "For example, Kiss1 (kisspeptin gene)- and Gpr54 (kisspeptin receptor gene)-deficient mice, rats, and humans are infertile and suffering for hypogonadotropic hypogonadism." (PMID 40507818, 2025). "Congenital ablation of Dicer in Kiss1-expressing cells caused a profound state of hypogonadotropic hypogonadism (HH) in male and female KiDKO mice of 4–6 months of age, i.e., mature adult period, following the standard nomenclature of the Jackson Laboratory." (PMID 35945211, 2022). "Homogeneous mutation of either KISS1 or KISS1R is associated with hypogonadotropic hypogonadism and infertility." (PMID 35606759, 2022). "Humans with inactivating mutations of KISS1 or KISS1R display a phenotype of hypogonadotropic hypogonadism, whereas activating mutations of KISS1 or KISS1R causes central precocious puberty." (PMID 35757400, 2022). "We show here that congenital ablation of Dicer, the key enzyme for mature miRNA synthesis, in Kiss1 neurons caused a state of profound hypogonadotropic hypogonadism in mature adult mice of both sexes, with complete infertility." (PMID 35945211, 2022). "Mutations in the KISS1 gene or KISS1R can lead to idiopathic hypogonadotropic hypogonadism and delay pubertal maturation of the gonadotropic axis, suggesting that KISS1R is indispensable for normal GnRH secretion." (PMID 35606759, 2022). "Later, a Turkish group demonstrated that patients carrying inactivating mutations of the KISS1 gene also exhibited hypogonadotropic hypogonadism." (PMID 34566891, 2021). "As expected, inactivating mutations in the KISS1 gene (coding kisspeptin) also caused hypogonadotropic hypogonadism in humans." (PMID 34502135, 2021). "Mutations in the KISS1 gene also contribute to precocious puberty or hypogonadotropic hypogonadism, depending upon the nature of mutations." (PMID 34646652, 2021). "Inactivating mutations in genes encoding neurokinin B (NKB) or its receptor NK3R results in hypogonadotropic hypogonadism and failure to attain puberty in rodents and humans, a phenotype reminiscent of that of patients with mutations of Kiss1 or GPR54." (PMID 34925558, 2021). "Kisspeptin is a pivotal modulator of pubertal activation and gonadal maturation as the functional loss of Kiss1 or its receptor result in delayed puberty and hypogonadotropic hypogonadism." (PMID 32204355, 2020). "A disruption of kisspeptin signaling, resulting from inactivating mutations of the KiSS1R or KiSS1 gene, results in hypogonadotropic hypogonadism in humans and mice." (PMID 28650956, 2017). "Humans and mice with loss-of-function mutations of the genes encoding kisspeptins (Kiss1) or kisspeptin receptor (Kiss1r) are infertile due to hypogonadotropic hypogonadism." (PMID 23762577, 2012). "The gene encoding kisspeptin (Kiss1) has beendemonstrated to be mutated in some cases of hypogonadotropic hypogonadism and to be upregulated in someinstances of precocious puberty." (PMID 21603196, 2011). "Admittedly, congenital Kiss1 null mice display hypogonadotropic hypogonadism, which might cause some developmental defects due to lower sex steroid levels." (PMID 38861336, 2024). "Here, we report that congenital ablation of the microRNA-synthesizing enzyme, Dicer, in Kiss1 cells, causes late-onset hypogonadotropic hypogonadism in both sexes, but is compatible with pubertal initiation and preserved Kiss1 neuronal populations at the infantile/juvenile period." (PMID 35945211, 2022).
hypogonadotropic hypogonadism (continued). "Notably, loss or gain of function mutations in either Kiss1 or Kiss1 receptor (Kiss1R) genes respectively cause hypogonadotropic hypogonadism or precocious puberty in mice and humans." (PMID 33573212, 2021). "Additionally, loss-of-function of KISS1 is associated with hypogonadotropic hypogonadism leading to reproductive function failure and female infertility." (PMID 31745224, 2019). "A wealth of data have conclusively documented that Kiss1 and Grp54 are essential for the acquisition and maintenance of reproductive capacity in mammals, including humans; mice and humans harboring inactivating mutations of these genes suffer impuberism and hypogonadotropic hypogonadism." (PMID 35945211, 2022). "KISS1 gene mutations and subsequent KISS1/KISS1R system dysregulation can lead to a range of idiopathic clinical symptoms, such as hypogonadotropic hypogonadism, central precocious puberty, and female infertility." (PMID 39558653, 2024). "To date, several Kiss1 or Gpr54 knockout rodents replicated hypogonadotropic hypogonadism as seen in humans." (PMID 34566891, 2021). "We used mice in which Cre recombinase was targeted to the Kiss1 locus and prevented Kiss1 protein synthesis; consequently, homozygous mice (Kiss1cre/cre) are Kiss1 KO and display severe hypogonadotropic hypogonadism." (PMID 30565563, 2018). "In search of the neuroendocrine substrate for the progressive central hypogonadism seen in KiDKO mice, we analyzed changes in Kiss1 neurons, Kiss1 expression, and kisspeptin content in the ARC and AVPV of male and female mice during the infantile-pubertal transition." (PMID 35945211, 2022). "In 2012, the phenotypes of patients carrying GPR54 mutations, i.e., hypogonadotropic hypogonadism and lack of puberty, was recapitulated in patients carrying inactivating mutations of the KISS1 gene (coding kisspeptin)." (PMID 31164866, 2019). "This first result indicated that the gonadotropic deficiency observed in nes::cre;Dmxl2wt/loxp mice was not due to a dramatic change of Kiss1 expression in the hypothalamus." (PMID 28209974, 2017). "Likewise, despite severe hypogonadotropic hypogonadism, a proportion of male and female Kiss1- and Kiss1r-knockout mice exhibited spermatogenesis and vaginal estrus, respectively, and Kiss1/Kiss1r double-heterozygotes are fertile with only mild effects on reproductive function." (PMID 23028524, 2012). "Loss-of-function mutations in KISS1/Kiss1 or the kisspeptin receptor (GPR54/Gpr54) genes causes infertility due to lack of pubertal development and hypogonadotropic hypogonadism in humans and mice." (PMID 22851226, 2013). "Loss-of-function mutations in kisspeptin (Kiss1/KISS1) or kisspeptin receptor (Gpr54/GPR54) genes cause infertility due to lack of pubertal maturation and hypogonadotropic hypogonadism in mice and humans." (PMID 23505551, 2013). "Hypothalamic KISS1 and KISS1R expressions decrease in many pathological conditions, resulting in the delay or absence of puberty in children, hypogonadotropic hypogonadism, and reproductive disorders." (PMID 39404414, 2024). "The importance of KISS1 in reproduction cannot be understated as whole-body knockouts of KISS1 or its receptor, GPR54/KISS1r, lead to hypogonadotropic hypogonadism, a condition where little to no sex hormones are produced, resulting in infertility and the loss of puberty." (PMID 34831343, 2021).
Infertility (30 papers, 2012 to 2025). "A review of the literature identified two studies that compared KISS1 levels in infertile couples based on the causative factor." (PMID 40429279, 2025). "Studies have showed that administering kisspeptin centrally can stimulate GnRH and LH secretion in various species, and mutations in the KISS1 gene can cause infertility." (PMID 38201210, 2023). "Kiss1 (kisspeptin gene)- and Gpr54 (kisspeptin receptor gene)-deficient mice, rats, and humans are infertile and associated with hypogonadotropic hypogonadism." (PMID 36813577, 2023). "The infertile phenotype in humans carrying inactivating mutations of the KISS1 or GPR54 genes was recapitulated in Kiss1 or Gpr54 knockout rodent models." (PMID 34502135, 2021). "Subsequent research has shown that the loss of Kiss1 gene function in mice and humans results in pubertal disorders and infertility symptoms similar to GPR54 knockout." (PMID 33551803, 2020). "The role of KISS1 in reproduction can be traced to the hypothalamus as the conditional knockout of KISS1r in GnRH neurons or KISS1 in hypothalamic neurons is enough to induce an infertile phenotype." (PMID 34831343, 2021). "Quennell and colleague have shown that hypothalamic Kiss1 mRNA expressions in high-fat-diet induced obese female mice, which are prone to infertility, are significantly lower than those fed with standard diet." (PMID 29976877, 2018). "Inactivating mutations in Kiss1 and the kisspeptin receptor (GPR54/Kiss1r) are associated with pubertal failure and infertility." (PMID 25093675, 2014). "The infertility of the Kiss1 and Gpr54 mutant mice prevents performing functional tests with mutant sperm." (PMID 24416028, 2013). "Based on the mechanism of sterility induction through the suppression of Kisspeptin neuron development and the decrease in cellular Kiss1 expression, it is likely that infertility in the male could also be induced by neonatal exposure to EB." (PMID 37316510, 2023). "Similarly, hypothalamic Kiss1 gene expression was reduced in female mice in which infertility had been induced via a high fat diet." (PMID 29976877, 2018). "Indeed, human genetic studies have associated loss of function mutations on either TAC3 or TACR3 genes (encoding NKB and its receptor NK3R respectively) with hypogonadism and infertility, similar to the phenotypes of Kiss1 or GPR54 mutants." (PMID 23543285, 2013). "Loss-of-function mutations in the genes encoding for kisspeptin (Kiss1) or its receptor (Kiss1r) or NKB (encoded by the Tac2 gene) and its receptor (NK3R, encoded by the Tacr3 gene) in humans and mice, are linked to hypogonadotropic-hypogonadism and infertility." (PMID 30565563, 2018). "In this study, the GnRH1, GnRHR, KISS1, KISS1R, TAC3 and TAC3R genes were analyzed in two unrelated nIHH patients successfully treated for infertility." (PMID 27544332, 2016). "Thus, resistance to insulin or leptin in Kiss1 neurons could lead to infertility." (PMID 25946091, 2015). "Kiss1-Cre LepR null mice showed no pubertal development and no improvement of the metabolic phenotype, remaining obese, diabetic and infertile." (PMID 23505551, 2013). "Mutations in KISS1/KISS1R cause congenital GnRH deficiency (characterized by delayed or absent puberty and infertility) or central precocious puberty, and aberrant kisspeptin signaling has been implicated in polycystic ovary syndrome (PCOS) and hypothalamic amenorrhea." (PMID 40430029, 2025). "Indeed, gene ablation of Kiss1, its receptor Gpr54, or the pituitary hormone, LHβ, resulted in hypogonadism and sterility, which supports the keen interest in targeting these components of the HPG in the treatment of infertility." (PMID 37316510, 2023). "Kiss1 PRKO mice lack PGR expression specifically within Kiss1 cells and are, perhaps surprisingly, not infertile; however, they do not display the characteristic OVX + E2-induced LH surge." (PMID 28790975, 2017).
central precocious puberty (21 papers, 2011 to 2025). "Several studies have reported mutations in GPR54 gene linked to idiopathic hypogonadotropic hypogonadism (IHH) and central precocious puberty, while mutations in Kiss1 gene have been linked to idiopathic CPP and normosmic IHH." (PMID 30993114, 2019). "Several studies underlined the role of KISS1 in the development of central precocious puberty." (PMID 37836499, 2023). "Activating mutation of Kiss1 or Kiss1R gene can cause central precocious puberty in humans." (PMID 27990162, 2016). "Otherwise, in some girls, an increased expression of the Kiss-1 gene leading to increased kisspeptin levels may be the cause of central precocious puberty, or could be the result of increased activation of the GPR54 signal system." (PMID 22672861, 2012). "Conversely, activating variants in KISS1R and KISS1 caused central precocious puberty (CPP)." (PMID 37272254, 2023). "Genetic etiology of Kiss1 and its receptor GPR54 genes is associated with hypogonadotropic hypogonadism and central precocious puberty." (PMID 35063020, 2022). "Brain tumors, brain trauma and gene mutations, such as KISS1 and KISS1R mutations, are known to cause central precocious puberty (CPP)." (PMID 28546864, 2017). "Mutations in the KISS1 gene or disorders of the kisspeptin/KISS1R system may lead to clinical symptoms such as idiopathic hypogonadotropic hypogonadism (iHH), central precocious puberty (CPP) and female infertility." (PMID 35837314, 2022). "Mutations in Delta-like homolog 1 (DLK1), the kisspeptin system (KISS1 and KISS1R), and the Makorin RING-finger protein 3 (MKRN3) gene have been identified in sporadic and familial cases of central precocious puberty." (PMID 39010901, 2024). "However, until now only the kisspeptin system KISS1/KISS1R, MKRN3, and DLK1 or Pref-1 identified in sporadic or familial central precocious puberty cases have been confirmed causal variants leading to CPP." (PMID 34748517, 2021). "Additionally, the data of AVPV as the other main group of Kiss1-expressed neuron bodies, median eminence as well as ARC in sexual development related disease model such as central precocious puberty is not included in this study." (PMID 35063020, 2022).
polycystic ovary syndrome (18 papers, 2018 to 2025). A disorder that manifests as multiple cysts on the ovaries. "Recently, the mRNA level of KISS1 has been found to be significantly upregulated in human granulosa lutein cells obtained from women with polycystic ovary syndrome, and KISS1 has been suggested to stimulate progesterone in GCs of pigs." (PMID 30759773, 2019). "Supporting our observations, KiSS-1 has been reported to regulate proliferation and apoptosis via PI3K/AKT/ERK signaling in ovarian granulosa cells in polycystic ovary syndrome." (PMID 41567980, 2025). "The aim of this study was to investigate the expression of anti-Mullerian hormone (AMH), kisspeptin 1 (KISS-1), and kisspeptin 1 receptor (KISS1r) in rat models of polycystic ovary syndrome (PCOS) and controlled ovarian stimulation (COS)." (PMID 31782699, 2020). "We identified CBX2 regulated genes associated with polycystic ovary syndrome (PCOS) such as TGFβ, MAP3K15 and DKK1, as well as genes implicated in premature ovarian failure (POF) (i.e. POF1B, BMP15 and HOXA13) and the pituitary deficiency (i.e. LHX4 and KISS1)." (PMID 31745224, 2019).